CSF3R (colony stimulating factor 3 receptor)
Diseases named in the same sentence as CSF3R in open-access papers (continued):
Sharing a sentence is not in itself a finding about the gene and the disease.
Sepsis (7 papers, 2015 to 2025). Sepsis is defined as life-threatening organ dysfunction caused by a dysregulated host response to infection. "Consistently, qRT‒PCR showed that the Csf3r mRNA level was indeed decreased in bone marrow neutrophils from Alkbh5-deficient mice compared with those from their WT littermates during sepsis." (PMID 38114747, 2024). "We found that, compared with normal samples, the expression levels of COMMD9 and CSF3R were all significantly down-regulated in samples from patients with sepsis compared to control samples." (PMID 37449204, 2023). "We identified COMMD9, CSF3R, and NUB1 as potentially biologically relevant genes and diagnostic markers for sepsis." (PMID 37449204, 2023). "As CSF3R activation is critical for neutrophil production, this could be an interesting target for treating individuals with sepsis." (PMID 40149573, 2025). "The proportion of CSF3R neutrophils and LYZ neutrophils was decreased in the sepsis group compared to healthy control group." (PMID 40149573, 2025). "We therefore investigated the relationship between COMMD9, CSF3R, and NUB1 expression and the infiltration of immune cells in specimens from patients with sepsis and healthy controls." (PMID 37449204, 2023). "We uncovered 50 DEGs between the cohorts that we further analyzed, resulting in prioritization of COMMD9, CSF3R, and NUB1 as potential biomarkers to diagnose sepsis." (PMID 37449204, 2023). "The main classes of drugs used for the evaluation of sepsis treatment are immunostimulatory drugs (immune targets CSF2RA/B, CSF3R), immunostimulatory cytokines (immune target is IFNGR1/2), and immunosuppressants (PDL1 and CTLA4)." (PMID 36389695, 2022). "We analyzed the immune targets of immune-related drugs to predict their potential use in sepsis and showed that nine target loci (CSF2RA/B, CSF3R, IFNGR1/2, IL7R, PDL1, CTLA4, and LAG3) differed in the high-/low-risk block." (PMID 36389695, 2022). "In the GSE72829 control and sepsis groups, C5AR1 (complement C5a receptor 1) and CSF3R (colony-stimulating factor 3 receptor) had degree 50 and 46, respectively." (PMID 33667236, 2021). "Recent similar studies have effectively utilized SVM-RFE to identify COMMD9, CSF3R, and NUB1 as potential biomarker genes for predicting sepsis, uncovering new mechanisms in disease pathogenesis that may offer opportunities for therapeutic intervention." (PMID 40535544, 2025). "This study is the first to propose and verify differential expression of COMMD9, CSF3R, and NUB1 in patients with sepsis, and ROC analysis confirmed that they may be useful as diagnostic biomarkers." (PMID 37449204, 2023). "In this study, we found that COMMD9, CSF3R, and NUB1 regulate immune cell infiltrate during sepsis, and we speculate that the activity of these genes may influence the development of sepsis." (PMID 37449204, 2023). "Ultimately, we identified COMMD9, CSF3R, and NUB1 as genes that could potentially be used as biomarkers to predict sepsis, which we confirmed by ROC analysis." (PMID 37449204, 2023). "Only three genes were identified by both of the approaches: COMMD9, CSF3R, and NUB1, suggesting these genes may be involved in sepsis diagnose." (PMID 37449204, 2023). "However, the expression and role of CSF3R in patients with sepsis are not known." (PMID 37449204, 2023). "We identified three genes, COMMD9, CSF3R, and NUB1, that were differentially expressed in sepsis compared to non-pathological specimens, and we correlated the differential expression of these genes with the immune cell composition of immune infiltrate." (PMID 37449204, 2023).
breast carcinoma (6 papers, 2020 to 2025). "RNA sequencing analysis further revealed that phosphoglucomutase 2-like 1 (PGM2L1) is a downstream target of the CSF3/CSF3R signaling, enhancing the glycolysis pathway and providing energy to support the malignant phenotype of breast cancer." (PMID 40185722, 2025). "In a recent study, using publicly available data sets, CSF3R was identified as one of the differentially expressed genes in a subset of immune-rich ER+ breast cancers." (PMID 33804486, 2021).
lupus (6 papers, 2013 to 2021). "In the past decade, three lupus susceptibility genes, CDKN2c, CSF3R, and mutant Skint6, have been identified from the Sle2c1 locus of the NZM2410 strain." (PMID 34720750, 2021). "Interestingly, high doses of G-CSF suppress lupus-like disease in at least one animal model and polymorphisms, the Csf3-r gene influence the development of lupus and RA." (PMID 29755457, 2018). "Thus, it is not unreasonable to hypothesize that sex-specific alterations in expression of CSF3-R could influence neutrophil phenotype and function and thereby differentially influence lupus pathogenesis in males and females." (PMID 29755457, 2018).
myelodysplastic syndrome (6 papers, 2019 to 2025). A clonal hematopoietic disorder characterized by dysplasia and ineffective hematopoiesis in one or more of the hematopoietic cell lines. "Cluster 1 was enriched with patients who had a prior diagnosis of myelodysplastic syndrome (MDS), mutations in the CSF3R gene, and mutations in the BCOR gene." (PMID 38232702, 2024). "Of these non-JAK2 mutation cases, the NRAS, CSF3R and TET2 c.4319_4329del; p.Arg1440Hisfs*34 were in the context of therapy-related disease; the remaining 4 other mutations (TET2, TET2, DNMT3A, and SF3B1) were in the context of disease progression from myelodysplastic syndrome." (PMID 36323674, 2022).
Splenomegaly (6 papers, 2014 to 2024). Abnormal increased size of the spleen. "In 2009 Plo and colleagues identified the first case of a germ line activating mutation in the CSF3R gene in a family with CIN associated with splenomegaly, based on the autosomal-dominant pattern of inheritance." (PMID 25431700, 2014). "It was also identified that the CSF3R T618I mutation exerted its effect through the JAK-STAT signaling pathway; hence, the splenomegaly and granulocytosis were responsive to treatment with ruxolitinib, a JAK inhibitor." (PMID 34249576, 2021). "While these disease-defining mutations serve as diagnostic markers if present, the WHO also allows for the possibility of CSF3R-negative disease in the face of chronic neutrophilia, splenomegaly, and the exclusion of reactive leukocytosis." (PMID 29440636, 2018).
acute leukemia (5 papers, 2016 to 2025). A clonal (malignant) hematopoietic disorder with an acute onset, affecting the bone marrow and the peripheral blood. "In the acute leukemia group, CSF3R mutations co-occurred with alterations in signaling pathway genes, including JAK3, STAT3, and NRAS." (PMID 40806796, 2025). "Another case reported a CNL patient with both a germline and a somatic CSF3R mutation (W791* and T618I) who developed mixed phenotypic acute leukemia upon acquiring a RUNX1 mutation." (PMID 39858009, 2025). "It is not entirely clear how activating and truncating CSF3R co-mutations alter progression to acute leukemia, although truncating mutations can enhance CSF3R-T618I-mediated growth in some in vitro assays." (PMID 35200567, 2022). "We observed copy neutral loss of heterozygosity (CN-LOH) at chromosome 1p at the time of transformation to acute leukemia, which substantiated the CSF3R co-mutated clone to variant allele frequencies >90% for both CSF3R mutations." (PMID 35200567, 2022). "Neither acquisition of a RUNX1 point mutation or CN-LOH at the CSF3R locus readily explain the mixed myeloid and lymphoid phenotype associated with transformation to acute leukemia." (PMID 35200567, 2022). "We report for the first time CNL transformation to acute leukemia of mixed phenotype (MPAL type) in the setting of a germline CSF3R-W791* truncation mutation located on the same allele as CSF3R-T618I, suggesting increased susceptibility for RUNX1-related clonal transformation." (PMID 35200567, 2022). "In contrast, cases with acute leukemia exhibited the lowest VAFs (median, 10%; range, 10–15%), suggesting a possible subclonal or secondary role of CSF3R in leukemogenesis." (PMID 40806796, 2025). "In this study, we investigated the role of co-occurring germline and somatic CSF3R mutations in CNL, and assessed the impact of clonal evolution on transformation to acute leukemia." (PMID 35200567, 2022). "Here we investigate the role of co-occurring CSF3R germline and somatic mutations and clonal evolution in CNL for transformation to acute leukemia based on a patient with early onset CNL." (PMID 35200567, 2022). "Here, we demonstrate that activating mutations in the granulocyte colony stimulating factor receptor (CSF3R), cooperate with loss of function mutations in the transcription factor CEBPA to promote acute leukemia development." (PMID 31784538, 2019). "Amongst acute leukemia patients in our cohort, one patient had RUNX1::RUNX1T1 translocation, while another had a biallelic CEBPA mutation, both of which are known to co-occur with CSF3R alterations." (PMID 40806796, 2025).
asthma (5 papers, 2017 to 2025). "The expression of CSF3 is higher in poorly controlled asthma, and inhibiting the signaling by neutralizing its receptor, CSF3R, decrease the production of mucus and hyperreactivity in the airway." (PMID 33362771, 2020). "Csf3r found in our upregulated DEGs (log2 = 1.96) following the results of other researchers, may play a role in asthma." (PMID 34803456, 2021).
melanoma (5 papers, 2014 to 2024). A malignant, usually aggressive tumor composed of atypical, neoplastic melanocytes. "According to the growing evidence, GCSF (CSF3) and its receptor GCSFR (CSF3R) are overexpressed in numerous malignancies, including melanoma, non-small cell lung cancer, bladder, prostate, and brain tumours." (PMID 38538691, 2024).
acute lymphoblastic leukemia (4 papers, 2021 to 2025). Leukemia with an acute onset, characterized by the presence of lymphoblasts in the bone marrow and the peripheral blood. "Of interest, CSF3R T618I mutated CEBPAbi subset was uniformly sensitive to JAK inhibitors, as also reported in CSF3R T618I mutated cases in other related disorders, i.e. T acute lymphoblastic leukemia and CNL." (PMID 39907800, 2025). "CSF3R mutations were found in two prior cases of early T-cell precursor acute lymphoblastic leukemia, in which the leukemic cells can also harbor both lymphoid and myeloid markers." (PMID 35200567, 2022). "Though dasatinib has not been used in large clinical trials, including MDS/MPN diseases that are associated with CSF3R truncated mutations, it has shown a favorable outcome when used in a patient with B-cell acute lymphoblastic leukemia (ALL) associated with a CSF3R mutation." (PMID 35949766, 2022).
COVID-19 (4 papers, 2022 to 2023). A disease caused by infection with severe acute respiratory syndrome coronavirus 2. "Particularly, many inflammation genes, such as C5AR1, CD55, CSF3R, CXCL8, FPR1, KLF6, and NFKB1A, were significantly upregulated in Neu and Mono cells of the bone marrow of COVID-19 patients." (PMID 37087411, 2023).
glioma (4 papers, 2020 to 2024). A benign or malignant brain and spinal cord tumor that arises from glial cells (astrocytes, oligodendrocytes, ependymal cells). "In the present study, we describe transcript levels of CSF3R in gliomas and their association with patient prognosis as assessed by overall survival (OS)." (PMID 38474265, 2024). "The present transcript analyses indicate that a significant association between high CSF3R mRNA levels and poorer prognosis measured by shorter OS was found in patients with gliomas." (PMID 38474265, 2024). "Analysis of glioma patient OS in relation to CSF3R/CD114 transcript levels in tumors showed that, when all glioma types were pooled together, higher CSF3R/CD114 expression was significantly associated with a poorer prognosis as assessed by shorter OS." (PMID 38474265, 2024). "We also observed that higher expression of CSF3R/CD114 in gliomas is associated with poorer outcome as measured by a shorter OS." (PMID 38474265, 2024). "Here, we describe CSF3R mRNA expression in human gliomas and their association with patient prognosis as assessed by overall survival (OS)." (PMID 38474265, 2024). "The main novel finding of the present study, obtained by analyzing public glioma and neural tissue data, is the association of poorer patient outcome assessed by a reduction in OS in patients with high CSF3R/CD114 mRNA expression in different types of glioma tumors." (PMID 38474265, 2024). "We found that the levels of CSF3R/CD114 transcripts are higher in a few different types of gliomas, namely astrocytoma, pilocytic astrocytoma, and GBM, in comparison to non-tumoral neural tissue." (PMID 38474265, 2024). "However, the potential role of CSF3R/CD114 as a biomarker in gliomas remains poorly understood and warrants further investigation." (PMID 38474265, 2024). "We went on to analyze CSF3R/CD114 expression in The Cancer Genome Atlas (TCGA) Brain Lower Grade Glioma (TCGA-LGG) cohort, which contains 513 glioma samples distributed across tumor types astrocytoma, oligoastrocytoma, and oligodendroglioma." (PMID 38474265, 2024).
B-cell acute lymphoblastic leukemia (3 papers, 2021 to 2025). A neoplasm of lymphoblasts committed to the B-cell lineage, typically composed of small to medium-sized blast cells. "Very recently, a truncation mutation in CSF3R in a patient with B-cell acute lymphoblastic leukemia was reported, and the patient was shown to have a favorable response to chemotherapy plus dasatinib." (PMID 34573308, 2021). "While CSF3R mutations/variants are mainly associated with myeloid diseases, they have also been identified particularly in B-cell acute lymphoblastic leukemia (B-ALL) and multiple myeloma (MM), most likely a consequence of CSF3R expression in early hematopoietic progenitors." (PMID 41154433, 2025). "Therefore, we hypothesize that these nonsynonymous potential activating CSF3R mutations could explain the pathogenesis of a few of the B-cell acute lymphoblastic leukemia patients." (PMID 34573308, 2021).
glioblastoma (3 papers, 2020 to 2024). The most malignant astrocytic tumor (WHO grade IV). "The correlation between GCSF (CSF3) and GCSFR (CSF3R) was analyzed, and highly correlate in glioblastoma patients with an optimum cut-off median at significance level p = 0.05." (PMID 38538691, 2024).
monoclonal gammopathies (3 papers, 2014 to 2024). "Compared to pure CNL, mutated CSF3R is infrequently reported in CNL cases associated with monoclonal gammopathies (MG)." (PMID 36568246, 2022). "No one with WHO-defined CNL but with a monoclonal gammopathy or lymphoid neoplasm had a CSF3R mutation." (PMID 25498990, 2014).
osteosarcoma (3 papers, 2021 to 2024). A usually aggressive malignant bone-forming mesenchymal neoplasm, predominantly affecting adolescents and young adults. "Furthermore, scRNA-seq analysis of six treatment-naïve osteosarcoma tumors, combined with a dataset of 22,035 cells from six osteosarcoma tumors, demonstrated that MDSCs were among the most abundant in the immunosuppressive milieu, as evidenced by MDSC hallmark genes (VCAN, CLEC4E, and CSF3R)." (PMID 39359731, 2024). "We developed a four-immune gene prognostic index of osteosarcoma, including CD79A, CSF3R, MTNR1B and NPPC." (PMID 33371790, 2021).
pneumococcal infection (3 papers, 2019 to 2023). Infections with bacteria of the species streptococcus pneumoniae. "Following pneumococcal infection, Csf3r−/− mice presented lower levels of myeloperoxidase (MPO), a marker of neutrophil recruitment, in lung homogenates at 36 hr post-infection." (PMID 37222419, 2023).
emphysema (2 papers, 2021 to 2025). "Importantly, we noted in male airway disease-dominant COPD an increased expression of macrophage associated genes, while in emphysema-dominant COPD neutrophil associated genes like CSF3R and CXCL1 were increased." (PMID 34145303, 2021). "The “response to stress” DEGs unique for E-dominant COPD include genes associated with neutrophils like CSF3R, MNDA and CXCL122–24 and this suggests that neutrophils might be selectively increased in the airway brush samples from emphysema-dominant disease." (PMID 34145303, 2021).
Leukocytosis (2 papers, 2024 to 2025). "Accordingly, CMML patient harboring CSF3R T618I mutation had a myeloproliferative phenotype with leukocytosis but showed concomitant dysplastic features, probably derived from the presence of double splicing-factor mutations, SRSF2 P95L and SF3B1 K666N." (PMID 39907800, 2025). "Leukocytosis, in cases without CSF3R mutation, is ≥25 × 109/L, but the ICC suggests lowering the threshold for leukocytosis in cases with a mutation in this gene to ≥13 × 109/L." (PMID 39682300, 2024).
periodontitis (2 papers, 2022 to 2024). An acute or chronic inflammatory process that affects the tissues that surround and support the teeth. "In periodontitis, MANSC1 was negatively correlated and the other four hub crosstalk genes (FMNL1, PLAUR, RNASE6, and TCIRG1) were positively correlated with five hub IRRGs, namely, AQP9, C5AR1, CD14, CSF3R, and PLAUR." (PMID 36545026, 2022).
prostate carcinoma (2 papers, 2022). A carcinoma that arises from epithelial cells of the prostate gland. "Patient 2 presented with a history of prostate cancer treated with radiation therapy and AML with normal cytogenetics and CEBPA (monoallelic), CSF3R, and TET2 mutations." (PMID 36077629, 2022). "However, by using logistic regression strategy, we found and validated that several VUS-containing genes (COL1A1, CSF3R, ERBB2, ITGB8, TSC1 and TSC2) in the PI3K-Akt signaling pathway can improve the predicting of metastasis in prostate cancer patients in Hong Kong and Shanghai cohorts." (PMID 36095024, 2022).
rectal cancer (2 papers, 2021). A primary or metastatic malignant neoplasm that affects the rectum. "The same approach for both colon and rectal cancers could be used to direct future studies of CSF3 and CSF3R involvement in tumor development and progression." (PMID 33606788, 2021). "Additionally, CSF3R expression is upregulated in CMS subtypes 1 and 4 in colon cancer (CC) and rectal cancer (RC)." (PMID 33606788, 2021).